ATF4 (activating transcription factor 4)
Diseases named in the same sentence as ATF4 in open-access papers (continued):
Sharing a sentence is not in itself a finding about the gene and the disease.
cancer (continued). "Despite elevated CHOP and ATF4 mRNA, FT246’s translational machinery selectively limits ISR gene production by enhancing overall protein translation, a mechanism not observed in cancer cells." (PMID 39349971, 2024). "Silencing of ATF4 or GCN2, however, reduced proliferation and clonogenic growth in different cancer cell lines in media lacking certain nonessential amino acids or glucose and clearly reduced xenograft growth." (PMID 33540663, 2021). "Activating transcription factor 4 (ATF4) is a member of the cAMP response element binding (CREB) protein family and has been reported to participate in cancer progression; however, its molecular mechanism is not fully understood." (PMID 33628101, 2021). "In conclusion, this study shows that JDP2 functions as a negative feedback regulator of the ATF4 pathway and modulates TRAIL sensitivity in cancer cells." (PMID 33108704, 2020). "However, it failed to block the induction of ATF4, ATF3, CHOP, GADD34, and TRIB3 proteins induced by DT-061 treatment in cancer cells." (PMID 39349971, 2024). "Given that DT-061-mediated activation of the ATF4-CHOP pathway does not fully rely on eIF2α phosphorylation, although is highly dependent on PP2A activity to trigger cancer cell death, we next ascertained whether these effects were mediated at the transcript level or via alternative mechanisms." (PMID 39349971, 2024). "However, ATF4 overexpression in HBE cells did not significantly promote cell invasion in HBE cells (p > 0.05), which indicates different functions of ATF4 in cancer cells compared with bronchial epithelial cells." (PMID 33628101, 2021). "In cancer cells, BAP1 removes monoubiquitin from ubiquitinated H2A at lysine 119 (H2Aub) on the SLC7A11 promoter to suppress its expression in cells treated with erastin but not RSL3, and this effect does not require the transcription factors NRF2 and activating transcription factor 4 (ATF4)." (PMID 33294126, 2020). "However, little or no ATF4 activation or mTOR suppression was detected upon OXPHOS inhibition in resistant cancer cells (CFPAC‐1, 786‐O, and SF126) under the same treatments, suggesting very limited induction of cellular stress responses in these cancer cells upon OXPHOS inhibition." (PMID 36382559, 2022).
infection (81 papers, 2014 to 2025). The state of being infected such as from the introduction of a foreign agent such as serum, vaccine, antigenic substance or organism. "Indeed, the treatment of cells with tunicamycin, an inhibitor of N-linked glycan biosynthesis that activates the ISR and thus ATF4, was sufficient to increase mtDNA levels independently of infection." (PMID 40811546, 2025). "As with HRI KO cells, OMA1 KO cells were deficient for the activation of ATF4 during infection." (PMID 40811546, 2025). "Alternatively, the PERK-eIF2α-ATF4-Nrf2 signaling cascade may be responding to general stress signals caused by infection." (PMID 37733353, 2023). "Moreover, in ATF4 (activating transcription factor 4)-knockdown macrophages, infection by L. amazonensis caused decreased Nrf2 expression, and nuclear translocation, reduced HO-1 expression, and increased nitric oxide production." (PMID 31998662, 2019). "UL38 is sufficient to promote cell survival by activating the PERK/eIF2α/ATF4 axis, while simultaneously suppressing pro-apoptotic IRE1-dependent JNK phosphorylation; ATF4 overexpression or JNK inhibition rescued cell viability following infection with UL38-deficient HCMV." (PMID 31877732, 2019). "However, in contrast to XBP-1, analysis of MCMV progression in ATF4 deficient hosts indicated a defect at late times p.i., a time that probably corresponds to the second round of infection." (PMID 25333725, 2014). "Third, the long-term effects of ATF4 inhibition on cartilage repair and joint function remain to be assessed, as chronic inhibition could potentially lead to unwanted side effects, such as impaired tissue repair or enhanced susceptibility to infection." (PMID 40782567, 2025). "The PERK and ATF4 genes were significantly inhibited at 24 and 36 hpi, but they were significantly over-expressed at the end of the infection (48 hpi)." (PMID 40248709, 2025). "To further assess ISR activation we next examined ATF4 translation during infection, which should occur rapidly following eIF2α phosphorylation." (PMID 39861909, 2025). "Because gene targets of ATF4 vary depending on its mechanism of activation, we next sought to define the host pathway upstream of ATF4 during infection." (PMID 40811546, 2025). "SVCV targets the immunoglobulin heavy chain-binding protein (BiP) and the activating transcription factor 4 (ATF4) during early infection to enhance viral RNA synthesis and translation." (PMID 40248709, 2025). "During infection of cultured mammalian cells with the intracellular pathogen Toxoplasma gondii, ATF4 increased mitochondrial DNA levels by driving the one-carbon metabolism processes that use folate in mitochondria." (PMID 40811546, 2025). "Experiments with PERK or ATF4 knockdown in infected macrophages have demonstrated a marked reduction in parasite burden, reinforcing the importance of this pathway in infection maintenance." (PMID 40149586, 2025). "We injected mice intraperitoneally with vehicle, tunicamycin, or mCherry-expressing Toxoplasma and measured the levels of ATF4 target transcripts in peritoneal exudate cells (PECs) isolated at 5 days post infection (dpi), near the peak of acute infection." (PMID 40811546, 2025). "To identify the ATF4 targets common to infection and ISR activation that mediated the increase in mtDNA levels, we compared the expression of a panel of ATF4 targets in uninfected cells, Toxoplasma-infected cells, and cells treated with tunicamycin." (PMID 40811546, 2025). "In this study, we observed that PTV-GXLZ2024 infection specifically activated the PERK-eIF2α-ATF4 pathway, while the ATF6 and IRE1 pathways remained unaffected." (PMID 41012628, 2025). "Infection drove increases in the levels of ATF4 targets Atf3, Shmt2, and Mthfd2, similar to our results in cultured cells." (PMID 40811546, 2025).
infection (continued). "In general, the three pathways were inhibited during the early phase of the SVCV infection and only the ATF4 and XBP1 pathways were significantly activated at the end of the infection cycle." (PMID 40248709, 2025). "Infection induced ATF4 as early as 6 hpi and maximally at 24 hpi, and ATF4 nuclear translocation was only evident in infected cells." (PMID 40811546, 2025). "A global analysis of the PERK pathway through the ATF4 transcription factor demonstrated activation at early stages of infection followed by a decrease at 24 hpi." (PMID 41157573, 2025). "This has been reported previously by other groups probing for ATF4 during infections with coronaviruses; however, it is still unclear why this occurs." (PMID 39861909, 2025). "As anticipated, our findings revealed that compared to the control group, infection with EHEC O157:H7 significantly increased the expression levels of ATF4 by 16.70% and CHOP by 29.84%." (PMID 40430759, 2025). "To test the role of ATF4 in increasing mtDNA levels during infection, we generated ATF4 knockout (KO) ES-2 cells using CRISPR-Cas9 technology." (PMID 40811546, 2025). "This increase in ATF4 transcript levels was further observed in primary human CD4+ T cells at day 5 post-infection." (PMID 38534416, 2024). "ATF4 protein expression increased from 12 to 24 hours following infection and remained steady until 48 hours post-infection." (PMID 39212382, 2024). "Knockdown of ATF4 by lentiviral shRNA infection reduced RNA levels of PSAT1 and SHMT2 in T315I-Bcr-Abl-32D cells." (PMID 38987326, 2024). "Altogether, these data strongly suggest a role for ATF4 in regulating HIV-1 replication both during the acute infection and the exit from latency." (PMID 38534416, 2024). "It was first described in Jurkat T cells, in which ATF4 was up-regulated at both the transcript and protein levels 8 h post-infection and remained elevated 48 h later." (PMID 38534416, 2024). "Elevated ATF4 expression indicated that the ISR pathway was activated during ZIKV PRVABC59 infection, which in turn stimulated ATF3 expression and downstream targets like CHOP for stress management." (PMID 39212382, 2024). "Studies have reported activation of GCN2 by pathogenic microbes: infection stimulates GCN2 in the gut, which triggers a translational block and promotes immune response through the ATF4-4E-BP axis." (PMID 37294006, 2023). "A previous study demonstrated that the porcine reproductive and respiratory syndrome virus (PRRSV) targets the UPR master regulator Bip for degradation and activates both the XBP1s and ATF4 signaling branches at the early stage of infection." (PMID 35321314, 2022). "The PERK branch of UPR-associated genes, including ATF4, ATF5 CHAC1, PDI, and DDIT3, were upregulated upon infection." (PMID 35368019, 2022). "Only ATF6 activation is detected during early infection while the activity of the eIF2alpha/ATF4 signaling is increased at the final stage of HSV-1 replication, suggesting that HSV-1 disarms the unfolded protein response in the early stages of infection." (PMID 35336954, 2022). "Tomatidine has inhibited dengue virus mainly at late stages of infection towards all dengue virus serotypes and controlled the activating transcription factor 4 (ATF4) expression." (PMID 34957305, 2021). "Here, we show that TB40/E infection increases ATF4 protein levels by 48 to 120 hpi via a PERK-dependent mechanism." (PMID 33947752, 2021). "We find that infection increases ELOVL7 protein levels by a PERK-dependent mechanism with kinetics similar to those of ATF4 expression." (PMID 33947752, 2021). "The addition of 100-fold arginine to the medium significantly delayed and lowered levels of host eIF2α-P and ATF4 mRNA during infection; similar results were obtained with just a 10-fold supplementation of arginine to the DMEM medium." (PMID 31194856, 2019).
infection (continued). "We then demonstrated that TMUV activated the PERK pathway in the early stage of infection, resulting in upregulation of ATF4, GADD34 and CHOP, with CHOP induction leading to caspase-3 activation." (PMID 30670030, 2019). "ATF4 and SMAD4 each associated with suppression of target genes in the WT BMM response to WNV while suppression is lost in the DKO BMM response to infection (compare left and right panels, respectively)." (PMID 31409781, 2019). "In this study, ATF4 expression increased significantly after 12 h post-infection, resulting in the induction of CHOP and in turn expression of GADD34." (PMID 30670030, 2019). "Infection of these cells with PRRSV revealed a reduction in virus titers when either ATF4 or XBP1s expression was reduced, but depletion of ATF6 did not have this effect." (PMID 31738790, 2019). "To learn when ATF4 is redirected to viral RTCs, we used immunofluorescence staining at different times after infection." (PMID 31738790, 2019). "Even though UL148 promotes ATF4 expression, likely via PERK activation, viruses that lack UL148 nonetheless still cause high levels of ATF4 accumulation at late times during infection, which is when viral late gene products, such a gB, are robustly expressed." (PMID 31822584, 2019). "As inflammation subsided, the expression of ATF4 returned to normal 10 days after infection (P > 0.05)." (PMID 30647960, 2018). "Compared with controls, ATF4 protein was degraded in infected mouse corneas at 1 day after infection (P < 0.05), then elevated at 3 days, and persisted up to 7 days (P < 0.05)." (PMID 30647960, 2018). "Compared with controls, ATF4 protein levels were elevated in infected mouse corneas at 3 days after infection (P < 0.05) and then started to degrade by 5 days (P < 0.05)." (PMID 30647960, 2018). "With TLR4 inhibitor pretreatment, ATF4 protein levels in infected mouse corneas at 1 day after infection and HCECs at 16 hours after A. fumigatus infection were significantly suppressed (P < 0.05, respectively)." (PMID 30647960, 2018). "After infection, the initial accumulation of P-eIF2α initiates the transcription of ATF4, which in turn upregulates the expression of unfolded protein response (UPR)-associated genes, including PPP1R15A and CHOP (an inducer of apoptosis)." (PMID 28860602, 2017). "To determine the role of ATF4 activation on the induction of ARE promoters in the context of the infection, we first carried out luciferase reporter expression under the control of the 3XARE promoter construct." (PMID 29213084, 2017). "The increased eIF2α phosphorylation during infection between 96 and 192 hpi resulted in a moderate inhibition of protein synthesis, as was apparent by the increase of ATF4 expression." (PMID 28202752, 2017). "Infection of TLR4-KO macrophages led to a remarkable reduction of ATF4 nuclear translocation when compared with infected wild-type cells." (PMID 29213084, 2017). "In HSV-1 infection, increased accumulation of ATF4 was detected at the final stage of the infection coincident with the completion of virion assembly and egress." (PMID 28202752, 2017). "In the present study, siRNA knockdown of ATF4 was found to significantly reduce the upregulation of GSH levels by WNV-infection and siRNA knockdown of either Nrf2 or ATF4 reduced the ability of WNV-infected cells to inhibit Ars-induced SG formation." (PMID 28241074, 2017). "ATF4 protein levels were analyzed by Western blotting of cell lysates harvested at different times after infection of BHK cells with WNV (MOI of 1)." (PMID 28241074, 2017). "Analysis of infection index demonstrated that ATF4 knockdown cells significantly reduces L. amazonensis burden in about 58% compared to scramble transfected cells." (PMID 29213084, 2017). "Incubation of cells with Ars for 30 min at different times after mock-infection also increased ATF4 levels." (PMID 28241074, 2017).
infection (continued). "Our data demonstrates that Leishmania parasites activate the PERK/eIF2α/ATF-4 pathway in cultured macrophages and infected human tissue and that this pathway is important for parasite survival and progression of the infection." (PMID 29213084, 2017). "Herpes simplex virus-1 was found to disarm UPR in early stages of infection, but induced eIF2α/ATF4 signaling at the final stage of its replication." (PMID 26907328, 2016). "In response to lenti-shATF4, ATF4 mRNA was downregulated by over 80% at 4 days after infection of either neuron type and remained so for at least 12 days." (PMID 27841340, 2016). "Two stable clones derived from KMS-11 cells with suppressed basal expression levels of either ATF3 or ATF4 were established by infection with two different lentiviruses, each carrying a miRNA sequence targeting ATF3 or ATF4." (PMID 26636288, 2015). "We first used these lentiviruses to examine the effect of ATF4 knockdown on the density of immunostained PSD-95 (post-synaptic density protein 95) dendritic puncta in hippocampal neuron cultures (infection at 6 DIV and assessed at 19 DIV)." (PMID 25071442, 2014). "High over-expression of ATF4 (>20-fold) induced signs of neuronal degeneration by 10 days and death after greater than 2 weeks following infection." (PMID 25071442, 2014). "However, restoring the ATF4 level via Ad-ATF4 infection led to decreased levels of GPX4 and phosphorylated mTOR, S6, and 4EBP1 by erastin, suggesting that ATF4 mediates the erastin-induced mTOR inhibition and the subsequent activation of ferroptosis signaling." (PMID 40227255, 2025). "To determine whether the ISR or mTORC1 mediated ATF4 activation during infection, we generated mouse embryonic stem cells cells (mESCs) deficient for eIF2α phosphorylation (eIF2αS51A)." (PMID 40811546, 2025). "Notably, ATF4 protein expression was progressively downregulated throughout the infection, while downstream CHOP protein levels remained unchanged, indicating an incomplete UPR induced by PTV-GXLZ2024." (PMID 41012628, 2025). "Nevertheless, we observed a slight increase in ATF4 protein levels during infection in both infected ADAR1 WT and infected KO cells compared to mock-infected cells, but in KO cells ATF4 expression increased dramatically towards the end of infection, further indicating translational arrest." (PMID 40198737, 2025). "Notably, infection provoked endoplasmic reticulum (ER) stress through the PERK/eIF2α/ATF4/CHOP pathway, as evidenced by ER expansion, ribosomal detachment, and mitochondrial damage." (PMID 40665414, 2025). "We next assessed the effect of ATF4 ablation on mito-1C metabolism during infection." (PMID 40811546, 2025). "HRI was required for the induction of ATF4 during infection." (PMID 40811546, 2025). "Notably, ATF4 expression gradually decreased during infection, whereas CHOP protein levels remained constant." (PMID 41012628, 2025). "We thus sought to address the role of ATF4 in mtDNA dynamics during infection." (PMID 40811546, 2025). "Importantly, Stat6 phosphorylation as well as Dclk1 induction were severely impaired in intestines from TgAtf4IEC mice 7 days post-infection, suggesting that tuft cell amplification was abolished upon Atf4 overexpression in vivo." (PMID 39085648, 2024). "Thus, ATF4 has a dual role in promoting cell survival or cell death, but also in limiting infection or participating in viral replication." (PMID 38534416, 2024). "GADD45B was stable over time, and ATF4 had minor changes starting at 3 h post-infection." (PMID 36768954, 2023). "Indeed, our data indicated that rt269L infection can trigger the PERK–eIF2α–ATF4 axis, in turn contributing to improved mitochondrial dynamics and energetics in infected hepatocytes via autophagy/mitophagy induction." (PMID 36997871, 2023). "Additionally, the protein expression of GRP78, EIF2α, and ATF4 were also markedly increased after infection." (PMID 35327108, 2022).